CPNE2 (copine 2)
Description:
Calcium-dependent phospholipid-binding protein that plays a role in calcium-mediated intracellular processes. Exhibits calcium-dependent cell membrane binding properties.
Synonyms: CPN2; COPN2
Tractability: Antibody: UniProt places it where antibodies can reach, with medium confidence; its Gene Ontology location is reachable by antibodies, with medium confidence. PROTAC: ubiquitination databases record sites on it; its protein half-life has been measured.
Gene: Protein-coding gene on chromosome 16 (57,092,549 to 57,148,369, forward strand). Ensembl gene ENSG00000140848.
Subcellular location: Cytoplasm; Nucleus; Cell membrane
Subcellular location (Human Protein Atlas): Cytosol; Mitochondria; Nucleoplasm
Gene Ontology:
Molecular function: protein binding; calcium-dependent phospholipid binding
Biological process: cellular response to calcium ion
Cellular component: extracellular exosome; cytoplasm; nucleus; plasma membrane
Genetic constraint (gnomAD): Loss-of-function variants: 42 observed, 70.46 expected, observed/expected ratio (o/e) 0.6, 90% interval 0.47 to 0.77. The upper end of that interval is the gene's LOEUF score, 0.77, which puts it in group 3 of 6, group 1 being the genes least tolerant of losing a copy. Missense variants: 587 observed, 739.25 expected, observed/expected ratio (o/e) 0.79, 90% interval 0.74 to 0.85. Synonymous variants: 294 observed, 293.36 expected, observed/expected ratio (o/e) 1, 90% interval 0.91 to 1.1.
Homologues: Orthologues: chimpanzee CPNE2 (99% identical), macaque CPNE2 (99% identical), dog CPNE2 (97% identical), guinea pig CPNE2 (96% identical), pig CPNE2 (96% identical), mouse Cpne2 (95% identical), rat Cpne2 (95% identical), tropical clawed frog cpne2 (82% identical), zebrafish cpne2 (79% identical), rabbit CPNE2 (71% identical), Caenorhabditis elegans cpna-2 (40% identical), Caenorhabditis elegans cpna-4 (26% identical). Paralogues in human: CPNE3 (62% identical), CPNE1 (57% identical), CPNE7 (53% identical), CPNE4 (52% identical), CPNE5 (52% identical), CPNE8 (51% identical), CPNE6 (50% identical), CPNE9 (48% identical).
Diseases named in the same sentence as CPNE2 in open-access papers:
CPNE2 is named in the same sentence as 1 disease in open-access papers, as found by Europe PMC text mining. Sharing a sentence is not in itself a finding about the gene and the disease.
CPNE2 shares sentences with these, for which no sentence is quoted: glioblastoma (2 papers).